FOXO1 (forkhead box O1)
Diseases named in the same sentence as FOXO1 in open-access papers (continued):
Sharing a sentence is not in itself a finding about the gene and the disease.
leukemia (24 papers, 2013 to 2025). A malignant (clonal) hematologic disorder, involving hematopoietic stem cells and characterized by the presence of primitive or atypical myeloid or lymphoid cells in the bone marrow and the blood. "For example, upregulation of FOXO1 in AML with a RUNX1 mutation has been reported to help the growth of leukemia cells and inhibit the differentiation of CD34 + hematopoietic stem and progenitor cells." (PMID 38007419, 2023). "We found that BCR-ABL1-transformed FoxO1fl/fl caused fatal leukemia within 2 weeks, while deleting FoxO1 by Tam-induced Cre-ERT2 activation reduced the leukemic cell burden and prolonged the survival time of respective mice." (PMID 32581241, 2020). "Additionally, FoxO1 and FoxO3 are frequently mutated or hyper-upregulated in leukemia, and pharmacological inhibition of FoxO1 dramatically reduces the aberrant growth of leukemia, indicating the fundamental roles of FoxO1 and FoxO3 in blood cancer." (PMID 37594999, 2023). "As both FOXO3 and FOXO1 inhibited leukaemia growth in our assays, we treated 697 and REH cells with Selinexor to increase pan-FOXO activity, achieving IC50 in the 50–100 nanomolar range." (PMID 36670235, 2023). "Our investigation of the TF pair FOXO1:ETV6 and its cooperativity-driven association with clinical features in CLL exemplifies this clearly and is reinforced by the observation of a FOXO1:ETV6 gene fusion in leukemia patients." (PMID 31913281, 2020). "Later, FOXO1 was identified as a critical survival factor in AML1-ETO leukemia, which appeared to be highly sensitive to AS1842856." (PMID 31557894, 2019). "In addition, the activity of FOXO1 has been reported to affect the antineoplastic drug sensitivity of AML cells, and has been proposed as a therapeutic for leukemia with RUNX1 mutations." (PMID 38007419, 2023). "In leukemia, miR-9 targets FoxOs (FoxO1 and FoxO3) to promote cell differentiation." (PMID 26593208, 2015). "We relate this FOXO3-specific leukaemia-protective role to suppression of glycolysis based on integrated analysis of CRISPR-data and gene sets induced or suppressed by FOXO1 and FOXO3." (PMID 36670235, 2023). "Next, we knocked down FOXO1 expression in Nalm6, a B-ALL leukemia cell line, and then examined the drug response." (PMID 33262946, 2020). "In addition, FOXK2, FOXL1, FOXO1, and FOXP3 were differentially expressed in at least six subtypes of leukemia." (PMID 36292640, 2022). "To test our hypothesis, we retrieved and analyzed the FOXO1 expression data from the Pediatric Cancer Genome Project (PCGP) and found that FOXO1 gene expression was the highest in ETV6-RUNX1 ALL and lowest in infantile leukemia." (PMID 33262946, 2020). "Both TFs have also been described as putative tumor suppressors in lymphomas, yet the extent of the cooperativity-driven functional impact on leukemia relative to other FOXO1-Ets combinations has not been understood nor quantified." (PMID 31913281, 2020). "To provide further evidence for the important role of FOXO1 in leukemogenesis in vivo, we injected BCR-ABL1-transformed FoxO1fl/fl cells into sublethally irradiated NOD/SCID recipient mice and monitored development of leukemia after deletion of FoxO1 as compared with controls in vivo." (PMID 32581241, 2020).
Glucose intolerance (23 papers, 2010 to 2025). Glucose intolerance (GI) can be defined as dysglycemia that comprises both prediabetes and diabetes. "In the lean animals, adipocyte Fpn deletion using a mouse model of AP2 Cre and Fpnfl/fl caused systemic glucose intolerance by downregulating the production of adiponectin through decreased acetylation of FOXO1 and a co-repressive effect by FOXO1’s binding to a PPARγ response element." (PMID 33133674, 2020). "In the current study, glucose intolerance is increased substantially in HFD fed mice with several folds increase in FOXO-1." (PMID 33076522, 2020). "Furthermore, glucose intolerance in db/db diabetic mice was worsened when FoxO1 was knocked out in the pancreas as well as when FoxO1 was knocked out explicitly in β-cells." (PMID 37941908, 2023). "Additionally, β-cell-specific knockout FoxO1 in db/db mice showed more severe glucose intolerance compared with control db/db mice, indicating the protective effect of FoxO1 in β cells." (PMID 27861641, 2016). "Furthermore, actions of the orexigenic melanin-concentrating hormone (MCH) in the ARC that promote hyperphagia, adipocyte lipid storage, and glucose intolerance are dependent on SIRT1 and FoxO1 activation." (PMID 37941908, 2023). "However, SIRT6 regulates glucose sensing in pancreatic β cells, and by suppressing SIRT6, in pancreatic β-cells, forkhead box protein O1 (FOXO1) is deacetylated and pancreatic and duodenal homeobox 1 (PDX1) and GLUT2 expression is diminished inducing systemic glucose intolerance." (PMID 35008779, 2021).
Infertility (22 papers, 2016 to 2025). "Knockdown of FoxO1 in mice model disrupts the feto-maternal cross-talk, which in turn caused implantation failure and infertility in mice." (PMID 40421018, 2025). "The granulosa-specific deletion of Foxo1/3 resulted in the altered expression of specific genes associated with follicle growth compared to apoptosis and infertility." (PMID 34201585, 2021). "In this study, we determined that ablation of FOXO1 results in infertility due to a uterine defect associated with inability of the blastocyst to invade the endometrial epithelium following an incomplete attachment reaction on the surface of the endometrium." (PMID 30452456, 2018). "Given the potential indirect influence of male-factor infertility on endometrial receptivity, we additionally examined the expression of key endometrial functional markers—FOXO1, HAND2, HOXA10, and KI67—in both groups." (PMID 41199770, 2025). "We analyzed the expression of m6A, METTL3, and forkhead box O1 (FOXO1) in ESCs from normal fertile women (the ND group) or women with endometriosis-related infertility (the ED group)." (PMID 37891533, 2023). "In summary, we revealed that METTL3-mediated m6A disrupts the cellular decidual process by promoting the YTHDF2-dependent decay of FOXO1 mRNA, thereby contributing to defective endometrial receptivity in infertile women with endometriosis." (PMID 37891533, 2023). "In the ovary, Foxo1/3 double‐knockout mice in granulosa cells from the secondary to the antral stage showed infertility." (PMID 33071644, 2020). "Uterine ablation of Foxo1 using the progesterone receptor Cre (PgrCre) mouse model resulted in infertility due to altered epithelial cell polarity and apoptosis, preventing the embryo from penetrating the luminal epithelium." (PMID 30452456, 2018). "The conditional ablation of Foxo1 using the PgrCre resulted in infertility due to disrupted implantation of the blastocyst." (PMID 30452456, 2018). "The findings of the present study indicate that METTL3-mediated m6A modification impairs the decidualization of endometrial stromal cells by promoting YTHDF2-dependent degradation of FOXO1 mRNA, thus affecting embryo implantation and resulting in endometriosis-related infertility to a large extent." (PMID 37891533, 2023). "Studies have also shown the role of FOXO1 gene in infertility." (PMID 33718760, 2021). "Indeed, conditional ablation of Foxo1 in the uterus resulted in infertility primarily due to retention of epithelial integrity during the implantation window that prevented embryo invasion." (PMID 31387263, 2019). "However, since we ablated Foxo1 in both the epithelial and stromal compartments of the uterus from birth, we cannot conclude that the resulting infertile phenotype is due solely to ablation of Foxo1 in the uterine epithelium or due to a developmental defect." (PMID 30452456, 2018). "Revealing the critical role of miR-181a in oxidative stress-induced FoxO1 activation and GC apoptosis more clearly elucidates the mechanism of follicular atresia, which is a key pathological process in ovarian dysfunction and infertility." (PMID 28981116, 2017). "Four transcription regulators (CCND1, FOXO1, CREB1, and HDAC4) were found to be targeted by DE-miRNAs, suggesting that they could be critical regulators in events associated with EMS and may play a role in infertility." (PMID 38002087, 2023). "Studies have shown that METTL3-regulated m6A modification facilitates FOXO1 mRNA decay through YTHDF2 in radiation-induced lung injury and endometriosis-related infertility." (PMID 41369154, 2025). "Of note, selective depletion of FOXO1 and FOXO3 in mouse GC leads to an infertile phenotype characterized by metabolic changes and the production of factors that exerts potent negative feedback to prevent gene expression of pituitary FSH (hub.BN role in the ivF network)." (PMID 34859047, 2021).
Infertility (continued). "The AKT-regulated transcription factor FOXO1 is an indispensable mediator of implantation because mice lacking uterine FOXO1 expression experience infertility due to failed implantation." (PMID 33048843, 2020). "Although this does rule out a developmental defect it does not rule out a role for stroma FOXO1 in the infertile phenotype." (PMID 30452456, 2018).
metabolic syndrome (22 papers, 2010 to 2025). A cluster of metabolic risk factors for CARDIOVASCULAR DISEASES and TYPE 2 DIABETES MELLITUS. "In mice, Foxo1 integrates insulin signaling with mitochondrialfunction, and inhibition of Foxo1 can improve hepatic metabolism during insulinresistance and the metabolic syndrome." (PMID 20351400, 2010). "FoxO1 and mTOR play key roles in the onset and progression of metabolic syndrome (MetS)." (PMID 38646331, 2024). "Particularly in hepatocytes, the overexpression of FoxO1 induces the accumulation of triglycerides, and targeting the FoxO1 expression in mouse livers may contribute to reversed metabolic syndrome." (PMID 35057469, 2022). "Foxo1 heterozygosity reduces the diabetic burden in mouse models of metabolic syndrome." (PMID 31615106, 2019). "FOXO1, which was down-regulated in the group of animals with high CLA-c9t11 content, is highly expressed in tissues such as pancreas, liver, skeletal muscle and adipose tissue in response to insulin and is associated with metabolic disorders as dyslipidemia." (PMID 27875996, 2016). "This study also showed that DHA supplementation restrained expression of FoxO1 and FoxO3 in pig adipocytes and human kidney HEK293T cells, suggesting that FoxO are potential therapeutic targets for DHA in ameliorating metabolic syndromes." (PMID 34371822, 2021). "Similarly, in C57BL/6 mice fed high-fat diets, GSPE reversed weight gain and dyslipidemia in mice, which was thought to be attributed to the ability of GSPE to downregulate the high-fat diet-induced increase of miR-96 and inhibition of mTOR/FOXO1 signaling." (PMID 37287997, 2023).
Cerebral ischemia (21 papers, 2017 to 2025). Restriction of arterial blood supply to the brain associated with insufficient oxygenation to support the metabolic requirements of the tissue. "During cerebral ischemia, the mechanisms of neuron death are associated with the activation of FoxO1 and the reduction of its inhibition by phosphorylation, which causes nuclear translocation as well as regulation of downstream signals." (PMID 36448290, 2023). "As the first found transcription factor in the FOXO family, FOXO1 was implicated as a crucial regulator of neuron survival in brain ischemia and is also a downstream target of SIRT141." (PMID 37132753, 2023). "Another important target for miR-183 is FOXO1, which has been found to be associated with cell apoptosis, cell cycle progression, and oxidative stress—a study has shown the mediating role of miR-183 in cerebral ischemia–reperfusion injury." (PMID 39337512, 2024). "FoxO1 and FoxO4 were implicated in antioxidant mechanisms after brain ischemia." (PMID 30559663, 2018). "Meanwhile, it has been reported that FoxO1 can promote the development of cerebral ischemia/reperfusion (CI/R) injury." (PMID 38549714, 2024). "The results suggested that the inhibition of AMPK activity eliminated the neuroprotective effect of 14, 15‐EET on cerebral ischemia reperfusion via the AMPK/SIRT1/ FoxO1 signal pathway." (PMID 37017405, 2023). "In contrast, deacetylation of FoxO1 has been also reported to play a neuroprotective role against neuronal apoptosis induced by oxidative stress after cerebral ischemia-reperfusion." (PMID 35371601, 2022). "SIRT1 has been shown to play a significant role in neuroprotection against cerebral ischemia by deacetylating and activating FoxO1." (PMID 35371601, 2022). "miR-182 promotes BBB failure by exacerbating endothelial cell apoptosis via the mTOR/forkhead box O1 (FOXO1) pathway during cerebral ischemia." (PMID 34374627, 2021). "There were 198 TFs identified after 6 h MCAO operation, and six TFs (Sox2, Smad3, FoxO1, Creb1, Egr,1 and Smad4) were considered as critical TFs in response to cerebral ischemia." (PMID 33414894, 2020). "Another role that FoxO1 plays during cerebral ischemia is repressing the expression of survivin." (PMID 35371601, 2022). "In contrast, our data revealed that miR-27a-3p could suppress cerebral ischemia-reperfusion injury by targeting FOXO1." (PMID 33875617, 2021). "Klotho was also proposed as a novel therapeutic target for cerebral ischemia, due to its antioxidative effect through AKT/FOXO1 pathway." (PMID 37985893, 2023). "Exercise is reported to exert its therapeutic influence on Alzheimer's disease through the targeting FoxO1(N. Zhao, Xia, & Xu, 2021) and by reducing brain damage by increasing Bcl‐2 and decreasing caspase‐3 and BAX expression in cerebral ischemia." (PMID 36448290, 2023). "Considering that FoxO1 is an important transcriptional regulator of PCK, exploring the way that FoxO1 regulates PCK and gluconeogenesis during cerebral ischemia will be a meaningful direction to explore in the future." (PMID 35371601, 2022). "Gene transfer of PRAS40 reduces infarction size of cerebral ischemia in rats by promoting the phosphorylation of Akt, FKHR (FOXO1), mTOR." (PMID 28978182, 2017).
lymphoma (21 papers, 2014 to 2025). A malignant (clonal) proliferation of B- lymphocytes or T- lymphocytes which involves the lymph nodes, bone marrow and/or extranodal sites. "During the pathogenesis of GC-derived lymphomas, the mutation of the transcription factor forkhead box O1 (FOXO1) enables co-option of GC-positive selection programs." (PMID 38932336, 2024). "The most reasonable candidate gene for the amplified region would be FOXO1, functioning as a transcriptional regulator and known to harbor recurrent oncogenic hotspot mutations in lymphomas enabling nuclear retention and avoidance of cytoplasmic inactivation." (PMID 38460675, 2024). "As it contributes to early B cell development and has been implicated as a TSG or as an oncogene in different lymphoma subtypes, we investigated the effects of FOXO1 on B-ALL growth." (PMID 36670235, 2023). "In conclusion, our results suggest that FOXO1 mutations in lymphoma may have opposite functional consequences on its transcriptional activity, further illustrating the complex role of this transcription factor in cancer." (PMID 35079069, 2022). "Moreover, studies in BL and B cell non-Hodgkin’s lymphomas have demonstrated FOXO1 mutation as a pro-oncogenic event in germinal center B cell–derived lymphomas owing to its pro-proliferative and antiapoptotic activity." (PMID 36282572, 2022). "Notably, FOXO1 has been implicated in the pathogenesis of GC-derived lymphomas." (PMID 31767615, 2019). "Diffuse large B cell lymphoma (DLBCL), a heterogenous lymphoma entity, can exhibit complex FoxO1 (in)activity." (PMID 39533662, 2025). "In mantle cell lymphoma (MCL), an aggressive lymphoma of pre‐GC cells, FoxO1 has been recently shown to play a master regulatory role, which exhibits certain properties reminiscent of the FoxO1‐driven B cell lineage commitment program." (PMID 39533662, 2025). "In MCL, FoxO1 serves as a master factor driving MCL‐lineage‐specific transcription programs that ensure the survival and proliferation of lymphoma cells, and a novel FoxO1 inhibitor has been tested in this context (cpd10)." (PMID 39533662, 2025). "Although FOXO1 is known as a tumor suppressor, it also contributes to malignant transformation in lymphomas." (PMID 38519029, 2024). "We have recently shown that FOXO1 activation almost completely abolished MYC protein expression in lymphoma cells." (PMID 26568463, 2015). "FoxO1, a well-known direct target of the miR-183/96/182 cluster, has been confirmed in various types of cancers, such as prostate, liver, breast, lymphoma and so on." (PMID 36290185, 2022). "Interestingly, several studies suggested pro-proliferative effects of wild-type FOXO1 and Nt mutants on lymphoma cells." (PMID 35079069, 2022). "Therefore, FOXO1 repression in PMBL contributes to the maintenance of the oncogenic program in this lymphoma type." (PMID 24977668, 2014). "In addition, high expression of FOXO1 was observed in lymphoma cell lines." (PMID 36292640, 2022). "Only FOXO1, BTG1, and MYD88 were in line with expectations, indicating that the abnormal transcriptional pattern for specialized lymphoma was very complicated due to the heterogeneity of lymphoma." (PMID 37700827, 2023). "FOXF1, FOXK2, FOXO1, FOXO3, and FOXP1 were differentially expressed in at least five subtypes of lymphoma." (PMID 36292640, 2022). "Examination of the link between FOXO1:ETV6 and lymphomas reveals that their joint expression levels improve patient clinical outcome stratification." (PMID 31913281, 2020). "We conclude that both down- and up-regulation of FOXO1 activity negatively influence the survival and proliferation of BL, indicating that, similar to BCP-ALL, FOXO1 acts as a rheostat in the oncogenic program of this utmost aggressive lymphoma." (PMID 31557894, 2019).
lymphoma (continued). "Foxo1 and Foxo3 in CD4+ T cells are the most important among Foxo family members because the T-DKO mice are lethal from eight weeks of age due to immunological disturbance, leading to lymphoma, enteritis, and digestive malabsorption." (PMID 31756626, 2019). "Therefore, FOXO1 copy number aberrations in PMBL are biased to gains rather than to losses and therefore do not contribute to FOXO1 downregulation in this lymphoma subtype." (PMID 24977668, 2014).